TBX1 (T-box transcription factor 1)
Diseases named in the same sentence as TBX1 in open-access papers (continued):
Sharing a sentence is not in itself a finding about the gene and the disease.
Holt-Oram syndrome (3 papers, 2016 to 2022). Holt-Oram syndrome (HOS) is the most common form of heart-hand syndrome and is characterized by skeletal abnormalities of the upper limbs and mild-to-severe congenital cardiac defects. "In humans, these heterozygous conditions can lead to syndromes, including Holt-Oram Syndrome (HOS, TBX5), ulna mammary syndrome (UMS, TBX3), DiGeorge syndrome (TBX1), spondylocostal dysostosis (TBX6) and cleft palate and ankyloglossia (TBX22)." (PMID 32855167, 2020).
Intellectual disability (3 papers, 2020 to 2024). "Shared aspects of these syndromes, such as intellectual disability, may be associated with an abnormal Tbx1 function." (PMID 36676170, 2023).
Obesity (3 papers, 2015 to 2019). Accumulation of substantial excess body fat. "We identified 3 genes at 22q11.2 (TBX1, COMT and MAPK1) that could confer susceptibility to obesity." (PMID 29441128, 2018). "In addition, statistical analysis showed that the ratio of expression level of TBX1 to TCF21 (TBX1/TCF21) in obesity group was significantly greater than those in normal and T2DM groups (P < 0.01)." (PMID 26273678, 2015). "Additionally, in Uygurs, visceral adipose tissue expression levels of TBX1 and TCF21 were greater in obesity group than in normal and T2DM groups and lower in T2DM group than in normal group (P < 0.01)." (PMID 26273678, 2015). "The TBX1 and TCF21 expression levels in the obesity group were significantly higher than those of normal and T2DM groups (P < 0.01); and the TBX1 and TCF21 expression levels in the T2DM group were significantly lower than those of normal and obesity groups (P < 0.01)." (PMID 26273678, 2015). "UCP1, PPARG coactivator 1 alpha (PPARGC1A), transcription factor A, mitochondrial (TFAM), T-box transcription factor 1 (TBX1), and solute carrier family 27 member 1 (SLC27A1) expression was assayed in SAT and VAT samples, obtained during sleeve gastrectomy from 62 patients with obesity." (PMID 31440209, 2019). "The ratio of expression level of TBX1 to TCF21 (TBX1/TCF21) in obesity group was significantly greater than those in normal and T2DM groups (P < 0.01), suggesting that the lipid metabolic activity of visceral adipose tissue in obesity individuals was lower than those in normal and T2DM individuals." (PMID 26273678, 2015).
otitis media (3 papers, 2015 to 2022). Inflammation of the anatomical structures of the middle ear, which is most often caused by an infectious process. "K5 cells have previously been shown to increase in number but retained their basal location in Tbx1 het mice with otitis media." (PMID 36299576, 2022). "One such approach is a dye clearance study that has elucidated the role of hypoplasia of veli palatini auditory-tube muscle in Df1/+ and Tbx1+/− mice with otitis media." (PMID 30898767, 2019).
skin tumor (3 papers, 2018 to 2021). "Similar results were observed in skin tumor of mice, in which TBX1 inhibited tumor growth and multilayered colony formation and induced cell cycle arrest." (PMID 33557670, 2021). "The downregulation of TBX1 in mouse skin may trigger skin tumor development." (PMID 30209892, 2018). "Previous work in another type of skin tumors in mice, squamous cell carcinoma (SCC), has shown that TBX1 is not expressed in these tumors and it was suggested that it might have tumor suppressor activity." (PMID 31963474, 2020).
atrioventricular septal defect (2 papers, 2015 to 2022). "It has been shown that the pSHF and DMP of Tbx1-/- embryos have altered expression profile, and the DMP is hypoplastic, which may be the cause of the atrioventricular septal defects (AVSDs) found in these mutants." (PMID 26382615, 2015).
autism spectrum disorder (2 papers, 2017). A spectrum of developmental disorders that includes autism, and Asperger syndrome. "Interestingly, several genes (Adcyap1, Cntnap2, Grid1, Nrxn1, Nrxn3, Ucn, Tbx1, and Nr2e1), that are associated with disorders, stress response, social behaviors or autism spectrum disorders, are up-regulated specifically in the hippocampus of Del/+ mice." (PMID 28704368, 2017).
cardiovascular malformations (2 papers, 2012 to 2022). "In the cardiovascular malformations associated with 16p11.2 microdeletion syndrome, our research found that 32% (8/25) of microdeletion regions of cardiovascular malformations contain TBX1, GJA5, HIRIP3, and other genes." (PMID 36553582, 2022).
cleidocranial dysplasia (2 papers, 2021 to 2022). "Loss of Tbx1 specifically in murine NCCs induces a similar phenotype to cleidocranial dysplasia and results in a lack of the hyoid body and fusion to the thyroid cartilage." (PMID 34299147, 2021). "In addition, TBX1 could be a candidate gene for recessive inheritance of cleidocranial dysplasia (OMIM #216330)." (PMID 35645294, 2022).
diabetes (2 papers, 2021 to 2023). "However, our data show that Tbx1 expression in mouse embryos did not alter under maternal diabetes with or without PHZ treatment, which are in line with the findings of unchanged Cyp26b1 and Cyp26c1 expressions in diabetic pregnancy." (PMID 37616226, 2023). "Chronic training increased the mRNA level of PGC-1α of SAT by 1.2-fold and 1.6-fold in the control group and the pre-diabetes group, respectively, whereas no significant changes neither in the brown-fat-selective gene Prdm16 or other known browning genes TBX1, TMEM26, and CD137 for both groups." (PMID 33922998, 2021).
ear infection (2 papers, 2017 to 2019). A viral or bacterial infection that affects the external, middle, or inner ear. "The same variant in TBX1 that was associated with tonsillectomy and childhood ear infection (see earlier) was also found to be significantly associated with myringotomy (rs1978060, P = 3.34 × 10−10, OR = 1.17)." (PMID 28928442, 2017).
Inguinal hernia (2 papers, 2019 to 2025). Protrusion of the contents of the abdominal cavity through the inguinal canal. "Some studies have previously indicated a potential association of TBX1 with congenital diaphragmatic hernia and inguinal hernia in humans." (PMID 41257561, 2025). "Genetic studies from China revealed that DNA sequence variants (DSVs) might contribute to inguinal hernia development by changing the transcriptional activities of TBX1, TBX2, TBX3, Sirtuin 1, and GATA transcription factor 6 (GATA6) gene promoters." (PMID 31024927, 2019).
orofacial cleft (2 papers, 2017 to 2023). A disorder of facial skeleton that is characterized by cleft lip and/or cleft palate that result in feeding, speech and hearing problems caused by failures during development. "Several regions mapped to genes that have previously been implicated in the development of orofacial clefts (for example, TBX1, COL11A2, HOXA2, PDGFRA), and over 250 associations were novel." (PMID 28603561, 2017).
parathyroid adenoma (2 papers, 2016 to 2020). "Verdelli demonstrated that TBX1 silencing in HEK293 cells and parathyroid adenoma-derived cells increases the proportion of cells in the G0/G1 phase." (PMID 33575219, 2020).
prostate carcinoma (2 papers, 2020 to 2022). A carcinoma that arises from epithelial cells of the prostate gland. "T‐Box Transcription Factor 1 (TBX1), a gene encoding a developmental transcription factor and implicated in retinoic acid signalling, has also been associated with prostate cancer risk." (PMID 36178085, 2022). "A recent meta‐analysis of 87 040 individuals (43 303 prostate cancer cases and 43 737 controls) identified an intronic single‐nucleotide polymorphism in the TBX1 gene that was significantly associated with prostate cancer in both European and Japanese populations." (PMID 36178085, 2022). "TBX1 has been reported to have a hypermethylated cytosine guanine dinucleotide island around its second exon, which was related to prostate cancer (PCa) progression." (PMID 33575219, 2020). "TBX1 protein expression in 280 primary prostate carcinoma tissues and 120 normal prostate gland tissues was assessed using IHC." (PMID 33575219, 2020). "We found that TBX1 is overexpressed in primary prostate carcinoma and demonstrated that TBX1 functions as a tumor activator in PCa cells through epigenetic control, thereby increasing rRNA gene transcription." (PMID 33575219, 2020).
22q11 duplication syndrome (1 paper, 2013). "Previously generated BAC316.23 transgenic mice expressing 8–10 copies of human TBX1 also have developmental defects of the same tissues affected in Tbx1−/− null mice, resembling clinical features of a recently identified 22q11 duplication syndrome." (PMID 23971992, 2013).
acute kidney injury (1 paper, 2021). Sudden and sustained deterioration of the kidney function characterized by decreased glomerular filtration rate, increased serum creatinine or oliguria. "Zhao and colleagues found that rs62341639 and rs62341657 polymorphism on chromosome 4 near the APOL1 regulator IRF2 and rs9617814 and rs10854554 polymorphism on chromosome 22 close to the acute kidney injury-related gene TBX1 were associated with AKI development but without genome-wide significance." (PMID 34300206, 2021).
adrenal tumors (1 paper, 2022). "They assessed in the perirenal region of PPGL higher expression of UCP1, CIDEA, ELOVL3, EBF3, FBXO31 and LHX8, but not TNFSRF9, TBX1 or TMEM26, in comparison with seven subjects with non-functional adrenal tumors." (PMID 35327387, 2022).
atherosclerosis (1 paper, 2021). A disease characterized by the build-up of fatty material and calcium deposition in the arterial wall resulting in partial or complete occlusion of the arterial lumen.
Cachexia (1 paper, 2018). Severe weight loss, wasting of muscle, loss of appetite, and general debility related to a chronic disease. "Interestingly, beige fat-associated genes (Tmem26 and Tbx1) but not brown fat-associated genes (Eva1 and Pdk4) were upregulated in patients with late-stage cachexia." (PMID 29338749, 2018).
cardiac hypertrophy (1 paper, 2021). "We found that there were similar expression patterns between Tbx1 and VEGF‐C or VEGFR‐3 during the transition from adaptive cardiac hypertrophy to TAC‐induced HF, suggesting that Tbx1 may be involved in regulating VEGF‐C or VEGFR‐3 expression in the heart." (PMID 33783987, 2021).
cardiomyopathy (1 paper, 2021). A disease of the heart muscle or myocardium proper. "TBX1, a gene at 22q11.2 tied to heart development, had other chronic ischemic heart disease, unspecified (P = 0.001), endocarditis (P = 0.0046), cardiomyopathy (P = 0.0055), and coronary atherosclerosis (P = 0.0076) among its top 1% phenome associations." (PMID 34715901, 2021).
cat-eye syndrome (1 paper, 2022). Cat eye syndrome (CES) is a rare chromosomal disorder with a highly variable clinical presentation. "Thirdly, both case 20 (de novo) and case 21 (maternally inherited) involved 22q11.1q11.21 duplication affecting the morbid genes TBX1 (MIM: 602054) and CECR2 (MIM: 115470); furthermore, the duplication region partially overlapped with a critical region of cat eye syndrome (CES)." (PMID 35806909, 2022).
chronic myeloid leukemia (1 paper, 2023). "Accordingly, we detected aberrant expression of TBX1 in 10% of stem/progenitor-cell-derived chronic myeloid leukemia (CML) patients." (PMID 38203204, 2023). "Furthermore, we exploited this TBX-code to identify aberrantly expressed TBX1 in patients of chronic myeloid leukemia (CML)." (PMID 38203204, 2023).
colorectal cancer (1 paper, 2021). A primary or metastatic malignant neoplasm that affects the colon or rectum. "Tbx1 is targeted by miR-3651 in colorectal cancer, promoting cell proliferation; by miR-451a in cutaneous basal carcinoma, suppressing cell growth; and by miR-96 in dental epithelial progenitor cells." (PMID 34068962, 2021).
Corneal opacity (1 paper, 2025). A reduction of corneal clarity. "Among KC-specific TFs, Hand2 and Tbx1 are the major transcription factors that regulate vascularization, which is the main cause of corneal opacity." (PMID 39896421, 2025).
Cyanosis (1 paper, 2022). Bluish discoloration of the skin and mucosa due to poor circulation or inadequate oxygenation of arterial or capillary blood. "However, DA patency was not assessed in Tbx1 KO mice despite the cyanosis and neonatal lethality common in mouse models of PDA." (PMID 34350653, 2022).
Down syndrome (1 paper, 2025). "Additionally, in Down syndrome (DS) mouse models, like Ts1Rhr and Ts1Cje, Tbx1 gene expression showed significant downregulation in the brain, suggesting its potential role in delayed fetal brain development and postnatal psychiatric phenotypes associated with the condition." (PMID 40982554, 2025). "Altogether, investigating treatment for DGS to reestablish a normal TBX1 function will also be of interest for Down syndrome, not only for the craniofacial but also for the heart and brain function." (PMID 40982554, 2025).
Hyperglycemia (1 paper, 2023). An increased concentration of glucose in the blood. "Since Tbx1 is expressed in the second heart field progenitor cells and is altered by maternal diabetes, the prevalence of TBX1-associated CHDs may correlate with craniofacial defects upon exposure to maternal hyperglycemia." (PMID 38003449, 2023).
Infertility (1 paper, 2015). "In addition, 22q11.2DS mouse models are not reported to have a cilia defects and do not display any phenotypes normally associated with immotile cilia such as situs inversus or infertility, indicating that half the dose of Tbx1 is sufficient for normal cilia function." (PMID 25452432, 2015).
leukemia (1 paper, 2023). A malignant (clonal) hematologic disorder, involving hematopoietic stem cells and characterized by the presence of primitive or atypical myeloid or lymphoid cells in the bone marrow and the blood. "A comparison of selected gene activities in 93 leukemia cell lines using data from the Human Protein Atlas showed elevated expression of TBX1 and GATA1 and low levels of GNAI2 in K-562, confirming our findings." (PMID 38203204, 2023). "To search for TBX1-expressing model cell lines, we screened RNA-seq dataset LL-100, comprising a representative panel of 100 leukemia/lymphoma cell lines." (PMID 38203204, 2023).
MRKH syndrome (1 paper, 2021). "In cases of MRKH syndrome, recurrent microdeletions and microduplications (1q21,1; 2q12.1q14.1; 16p11.2; 17p14.3; 17q12; 22q11.21; 22q11.21q11.23) and mutations in genes located on these loci (RBM8A, PAX8, TBX1, TBX6, LHX, HNF1B, WNT4) have been identified." (PMID 33883018, 2021). "Genes other than TBX1 could be involved in the development of uterine malformations described in MRKH syndrome, such as SNAP29, or other genes in the same genetic pathway as TBX1." (PMID 33883018, 2021).
neuropathy (1 paper, 2022). A disorder affecting the nervous system that manifests with pain, tingling, numbness, and/or muscle weakness. "Specifically, these DEGs were associated with neuropathy-related pathways, such as GABRD, GABRP, TBX1, and SOX10, and inflammatory responses such as CXCL3, CXCL12, TNF, and IL6." (PMID 36147849, 2022).
osteoporosis (1 paper, 2021). A condition of reduced bone mass, with decreased cortical thickness and a decrease in the number and size of the trabeculae of cancellous bone (but normal chemical composition), resulting in increased fracture incidence. "These indicated that senescent osteoblast exosome-delivered miR-139-5p is a potential regulatory pathway for endothelial cell senescence by targeting TBX1, which might be an important mechanism for osteoblast regulating endothelial cell function during osteoporosis." (PMID 33954179, 2021).
Thymic aplasia (1 paper, 2021). "Moreover, Tbx1± embryos do not demonstrate significant thymus abnormalities, whereas thymic aplasia is a characteristic feature of Tbx1−/− embryos." (PMID 33987750, 2021).
thyroid (1 paper, 2018). "It is envisaged that lack of Fgf8 reduces the number of progenitors committed to a thyroid fate, which might at least partly explain thyroid dysgenesis in the absence of Tbx1." (PMID 29361553, 2018).
ulnar-mammary syndrome (1 paper, 2013). Ulnar-mammary syndrome (UMS) is a rare developmental disorder characterized by ulnar defects, mammary and apocrine gland hypoplasia and genital anomalies. "Expression of Tbx1 and Tbx3, the DiGeorge/velo-cardio-facial (DGS) and Ulnar-mammary syndrome (UMS) disease genes, was expanded in miR-17-92 mutant craniofacial structures." (PMID 24068957, 2013).
vitamin D deficiency (1 paper, 2025). A nutritional condition produced by a deficiency of VITAMIN D in the diet, insufficient production of vitamin D in the skin, inadequate absorption of vitamin D from the diet, or abnormal conversion of vitamin D to its bioactive metabolites. "This systematic review consolidates evidence for genetic (e.g., NR4A2, TBX1, MTHFR) and environmental (e.g., phthalates, consanguinity, vitamin D deficiency) risk factors in Saudi ASD populations, while highlighting neuroinflammation as a potential biomarker." (PMID 41246720, 2025).